HMGB1 (high mobility group box 1)
Diseases named in the same sentence as HMGB1 in open-access papers (continued):
Sharing a sentence is not in itself a finding about the gene and the disease.
colorectal cancer (147 papers, 2010 to 2026). A primary or metastatic malignant neoplasm that affects the colon or rectum. "Previous studies reported that GSDME-mediated pyroptosis promoted colitis-associated colorectal cancer by releasing HMGB1, which in turn induced tumor cell proliferation via ERK1/2 pathway." (PMID 39789615, 2025). "In vivo models of B-cell lymphoma and colorectal cancer demonstrated that melphalan causes immunogenic cell death, determined by surface-exposed calreticulin and release of high-mobility group box 1 (HMGB1)." (PMID 41160198, 2025). "Our data revealed only comparatively weak associations between increased HMGB1 expression and unfavorable tumor features in serous ovarian carcinoma, colorectal cancers, and squamous cell carcinomas." (PMID 40804938, 2025). "AOM/DSS-induced colorectal cancer in mice was associated with high expression of both HMGB1 and RAGE in cancer tissues." (PMID 40244228, 2025). "It was reported that GSDME-mediated pyroptosis triggered the release of HMGB1, leading to the development of colitis-associated colorectal cancer (CAC) via the activation of ERK1/2 signaling pathway." (PMID 36267972, 2022). "In colorectal cancer, cytoplasmic HMGB1 in tumor cells is associated with poor outcome, while nuclear HMGB1 is present in both normal and tumor cells." (PMID 31779212, 2019). "The association of HMGB1 polymorphisms with the risk of colorectal carcinoma was also investigated in a Chinese population." (PMID 29617336, 2018). "High pretherapeutic values of serum HMGB1 in patients with colorectal cancer liver metastases were associated with poor 2‐year overall survival." (PMID 27457217, 2016). "Co-expression of RAGE and High-mobility group protein B1 (HMGB1) has been substantially associated with colorectal cancer invasion and metastasis." (PMID 25860956, 2015). "The evaluation of serum HMGB1 levels is essential for evaluating both the diagnostic significance of HMGB1 in colorectal cancer and the inhibition of cancer progression by blocking serum HMGB1." (PMID 22496788, 2012). "Strong HMGB1 immunostaining was linked to nodal metastases in high-grade serous ovarian carcinomas (p = 0.0213) and colorectal cancers (p = 0.0137), as well as to high histological grade in a combined analysis of squamous cell carcinomas originating from 11 different organs (p = 0.0010)." (PMID 40804938, 2025). "Furthermore, GSDME-mediated pyroptosis can promote the occurrence and progression of colitis-associated colorectal cancer by releasing damage-associated molecular pattern molecules and high mobility group box 1 (HMGB1)." (PMID 39526199, 2024). "Studies also suggested that the signal path of HMGB1/RAGE could cause colorectal cancer to happen by activating the YAP1, and the higher levels of HMGB1 and RAGE could also give rise to glioma." (PMID 34369271, 2021). "Serum HMGB1 is higher in colorectal carcinoma and HMGB1 is a valuable diagnostic biomarker." (PMID 34867338, 2021). "HMGB1 overexpression is associated with poorer prognosis in colorectal cancer patients." (PMID 29868478, 2018). "Furthermore, a recent study showed HMGB1 to be significantly elevated in colorectal cancer patients to possibly influence the risk for sterile inflammation and hence idiosyncratic hepatotoxicity." (PMID 27058902, 2016). "HMGB1 expression has been reported to be significantly associated with tumor invasion, lymph node metastasis, distant metastasis, and Duke’s stage and inversely associated with overall survival in human colorectal carcinoma." (PMID 23866030, 2013). "Research in colorectal cancer has revealed that high-mobility group box 1 (HMGB1), engaging its receptor RAGE, activates the ERK1/2 pathway to phosphorylate and activate Drp1, thereby fostering chemoresistance." (PMID 41573644, 2025). "On the other hand, LPS induces pro-inflammatory cytokines (such as IL-1β, IL-6, and TNF-α) in a HMGB1-dependent manner to improve colorectal cancer progression." (PMID 40495163, 2025).
colorectal cancer (continued). "For example, it promotes tumorigenesis in colitis-associated colorectal cancer via the ERK1/2 pathway, and in collagen-induced arthritis, inhibition of the HMGB1/TLR4/STAT3 axis in M1 macrophages alleviates disease severity." (PMID 41009742, 2025). "These recombinant viruses induce pyroptosis in colorectal cancer cells accompanied by the release of HMGB1." (PMID 40082916, 2025). "Overall, HMGB1-targeted therapy shows potential across various cancer fields, including colorectal cancer and non-small-cell lung cancer (NCT01312467, NCT02186847, registered at ClinicalTrials.gov)." (PMID 41296391, 2025). "In colorectal cancer, HMGB1-dependent autophagy markedly upregulates ABCG2, P-gp, MRP2, and GST-π, whereas autophagy inhibition by 3-MA reverses these effects and restores drug sensitivity." (PMID 41465435, 2025). "For example, representative DAMP HMGB1 was reported to inhibit oxidative phosphorylation of colorectal cancer cells." (PMID 40862736, 2025). "In NPC, this occurs via GL’s disruption of the critical HMGB1-Ku70 interaction, while in colorectal cancer, it inhibits HMGB1 to promote DNA fragmentation and apoptosis." (PMID 41465435, 2025). "Herein, we observed that HMGB1 promotes the proliferation of colorectal cancer cells and enhances their resistance to radiation, suggesting that HMGB1 directly regulates the radioresistance of tumor cells." (PMID 41164196, 2025). "High mobility group box 1 (HMGB1) has been implicated in the development of various cancers, but its role in colorectal cancer (CRC) remains poorly understood." (PMID 40975711, 2025). "HMGB1-driven JNK and ERK activation in leukemia and colorectal cancer reinforces this autophagy-dependent apoptotic escape, while an HMGB1/c-Myc circuit mediates paclitaxel resistance in castration-resistant prostate cancer." (PMID 41465435, 2025). "For instance, MALAT1 increases HMGB1 levels in hepatic injury, colorectal cancer, and multiple myeloma, often acting as a competitive endogenous RNA (ceRNA) for miRNAs that target HMGB1." (PMID 40429961, 2025). "In colitis-associated colorectal cancer, GSDME-mediated pyroptosis promotes tumorigenesis through the release of HMGB1, which subsequently activates the ERK1/2 pathway to drive tumor cell proliferation." (PMID 41465435, 2025). "The expression of classical nuclear DAMPs, including HMGB1 and HSP90, was upregulated in BTZ-treated colorectal cancer cells and more significantly in B-Myb–deficient cells in vitro and in vivo." (PMID 38565963, 2024). "It has been confirmed that miR-495-3p down-regulates HMGB1 expression to inhibit cell proliferation and migration in colorectal cancer." (PMID 38079253, 2024). "Experimental evidence has shown that in colorectal cancer cells, extracellular HMGB1 activates ERK1/2 through its interaction with RAGE." (PMID 38529373, 2024). "This study further revealed that HMGB1-induced activation of ERK1/2 signaling leads to colorectal cancer carcinogenesis and proliferating cell nuclear antigen (PCNA) expression, which is a key proliferation marker indicating the rate at which cells multiply." (PMID 38725632, 2024). "In the growth processes of liver cancer, colon cancer, colorectal cancer, cervical cancer, prostate cancer, and pancreatic cancer, the HMGB1/RAGE axis can promote tumor migration and invasion through the NF-kB signaling pathway." (PMID 38529373, 2024). "In colorectal cancer, miR‐495 appears to inhibit cancer cell proliferation and migration by targeting HMGB1." (PMID 39261977, 2024). "Among the selected genes, HMGB1, a well-known tumor activator that promotes the metastasis of non-small cell lung cancer through NF-κB, plays a corresponding role in colorectal cancer by regulating ERK1/2 signaling, and is upregulated in human lung cancer." (PMID 37932766, 2023).
colorectal cancer (continued). "Studies with human colorectal cancer cells indicate that HMGB1 also reduces CD8+ T cell infiltration into the TME through a mechanism involving the regulation of microtubule-associated proteins." (PMID 36831371, 2023). "According to existing research results, HMGB1 regulates various signaling pathways during colorectal cancer development." (PMID 36709284, 2023). "Overall, we reveal that reduction of nuclear and emergence in cytoplasmic epithelial HMGB1 occurs in colorectal cancer." (PMID 36980751, 2023). "MAP7D2 interacts with the MYH9 protein to protect it from ubiquitin-mediated degradation, subsequently reducing the secretion of HMGB1 to inhibit the infiltration of CD8+ cytotoxic T lymphocytes in microsatellite-stable colorectal cancer." (PMID 37875476, 2023). "In colorectal cancer, chemotherapy induces ROS activation of HIF1α, which drives the transcription of high-mobility group protein B1 (HMGB1) in tumor cells, thereby promoting macrophage infiltration in tumors." (PMID 37004014, 2023). "We characterised subcellular epithelial cell expression of HMGB1 in the colorectal cancer (CRC) TMA (n = 650)." (PMID 36980751, 2023). "We demonstrate dynamic subcellular (nuclear and cytoplasmic) HMGB1 expression in lesions seen throughout different stages of colorectal cancer development." (PMID 36980751, 2023). "Wang and colleagues demonstrated positive nuclear expression with no cytoplasmic HMGB1 in normal colonic epithelium, as we do here, and emergence of cytoplasmic HMGB1 in their smaller cohort of adenomas (n = 68) and colorectal cancers (n = 369)." (PMID 36980751, 2023). "GSDME-mediated pyroptosis can promote the release of high-mobility group box-1 (HMGB1) to induce the proliferation of tumor cells and the development of colorectal cancer." (PMID 37313458, 2023). "For instance, oxidized HMGB1 has been shown to recruit MSCs into tumors, thereby increasing colorectal cancer stemness and facilitating liver metastasis." (PMID 37865637, 2023). "An immunofluorescence experiment was used to determine the overexpression of HMGB1 in the infected colorectal cancer cell lines using anti HMGB1 antibody." (PMID 35477503, 2022). "Research studies have shown that HMGB1 and HMGB2 are closely related to colorectal cancer and can be used as potential diagnostic and prognostic markers." (PMID 35712661, 2022). "The use of an HMGB1 inhibitor or a RAGE blocker to improve chemotherapeutic sensitivity in colorectal cancer is well-accepted." (PMID 35326612, 2022). "The results are consistent with those of reported publications wherein HMGB1 knockdown reduced growth and migration in the colorectal cancer model." (PMID 36230798, 2022). "Overexpression of HMGB1 is related to the growth, invasion and metastasis of multiple malignancies including gastric cancer, pancreatic cancer, colorectal cancer, and lung cancer." (PMID 35829833, 2022). "Similar with it, a finding in colorectal cancer reported that high-mobility group box 1 protein (HMGB1) secreted from tumor cells after chemoradiotherapy which promotes tumor cells regrowth, proliferation and metastasis." (PMID 34868997, 2021). "Our results are consistent with other studies performed on patients with gastric cancer, cervical cancer und hepatically metastasized colorectal cancer, in which HMGB1 showed prognostic value as well." (PMID 33672622, 2021). "Our previous studies indicated that the release of HMGB1 and infiltration of CD8+ TILs were significantly associated with favorable survival outcomes in colorectal cancer, especially in patients who received the neoCRT regimen." (PMID 33799527, 2021). "It has been reported that HMGB1 induces mitochondrial fission via the ERK/Drp1 signaling pathway in colorectal cancer." (PMID 34674708, 2021).
colorectal cancer (continued). "Antitumor events were promoted by the miR-34a-5p/HMGB1 axis in acute myeloid leukemia, cutaneous squamous cell carcinoma, cervical cancer, and colorectal cancers, and similar effects were exerted by miR-34a-3p/HMGB1 in retinoblastoma." (PMID 34073766, 2021). "Recently, PITPNA-AS1 was found for facilitating colorectal cancer cells' proliferation and metastasis through miRNA-129-5p/HMGB1 axis." (PMID 34055841, 2021). "5-Fluorouracil increases the frequency of tumour-infiltrating cytotoxic T lymphocytes in colorectal cancers, activating HMGB1 (High-Mobility Group Box 1) and ATP secretion." (PMID 33504012, 2021). "The mitoxanthrone can induce exposure of CARL in human colorectal cancer cells and the autophagic process via the release of ATP and HMGB1 from necrotic cells in pancreatic and breast cancer cells." (PMID 33504012, 2021). "When HMGB1 is passively released from dying tumour cells following chemotherapy in colorectal cancer, HMGB1 facilitates autophagy following cytotoxic insults for chemoresistance via its RAGE receptor via the MEK/ERK signaling pathway." (PMID 34194625, 2021). "In this context, chronic inflammation linked to HMGB1/TREM-1 interactions has been linked to the pathogenesis of HCC and colorectal cancer." (PMID 32664328, 2020). "To verify the intensity of the HMGB1 release, we tested the extracellular HMGB1 in other cancer cell lines—murine colorectal cancer cells CT26 and human epidermoid carcinoma cells A431." (PMID 32698492, 2020). "In a mouse model, anti-HMGB1 antibody therapy was reported to reduce colorectal cancer liver metastasis derived from a cell line expressing the highest level of HMGB1." (PMID 31399104, 2019). "Tissue or serum HMGB1 has been proved to be highly expressed in a variety of cancers, including laryngeal squamous cell carcinoma, gastric cancer, pancreatic cancer, colorectal cancer, and cervical cancer." (PMID 30962261, 2019). "Oxidized HMGB1 enhances apoptosis and chemosensitivity in pancreatic and colorectal cancer cell lines, whereas reduced HMGB1 promotes autophagy-mediated chemoresistance towards melphalan, oxaliplatin and paclitaxel." (PMID 30612957, 2019). "The level of HMGB1 expression was reported to be associated with lymph-node metastasis and advanced TNM stage in esophageal cancer, gastric cancer, colorectal cancer, head and neck cancer, and cervical cancer." (PMID 31399104, 2019). "The data reported here indicate the potential of extracellular HMGB1 released from colorectal cancer cells to exert a paracrine effect on surviving cancer cells enabling them to resist chemoradiotherapy." (PMID 30258050, 2018). "Consistently, we found that OXP, CAP, and CPT-11 promote the enhanced expression and secretion of HMGB1 in human colorectal cancer cells." (PMID 30258050, 2018). "In order to determine the relevant of our newly discovered pathway for necrotic cell-mediated tumor repopulation in human cancer, we evaluated HMGB1 status in cancer patients, especially in colorectal cancer patients." (PMID 29844348, 2018). "HMGB1-mediated autophagy modulates the sensitivity of colorectal cancer cells to Oxaliplatin via the MEK/ERK signaling pathway." (PMID 30258050, 2018). "Administration of anti-HMGB1 antibody inhibits liver metastasis of colorectal cancer, suggesting that HMGB1 is a promising target for metastasis inhibition." (PMID 28969092, 2017). "It has been demonstrated that during the development of colorectal cancer, serum HMGB1 increased, thus changes in opposite direction induced by NW training should be considered as a positive one." (PMID 28316011, 2017). "Fahmueller and coworkers showed in patients with liver metastases of colorectal cancer that serum HMGB1 increases as early as within 24 h in response to radioembolization." (PMID 27457217, 2016).
colorectal cancer (continued). "Based on the histological study and in vitro study, we propose that both apoptosis and necrosis play an important role in tumor progression, and both CC3 and HMGB1 are predictive markers of poor prognosis in colorectal cancer patients." (PMID 25986235, 2015). "Multivariate analysis using Cox proportional hazards model showed that TNM staging and HMGB1 were independent prognostic factors in patients with colorectal cancer (CRC) (p <0.01, p <0.001)." (PMID 25986235, 2015). "This study showed that the concentrations of HMGB1 in the culture medium of colorectal cancer cells and cleaved caspase-3 in the colorectal cancer cells were increased after radiation, which parallels the increase in PCNA, a well-known proliferative marker." (PMID 25986235, 2015). "In patients with colorectal cancer the coexpression of RAGE and HMGB1 was associated with invasion and metastasis." (PMID 24705787, 2014). "ELISAs were performed to evaluate serum HMGB1 levels in a large series of colorectal cancer patients." (PMID 22496788, 2012). "HMGB1 was detected in the serum, and HMGB1 levels were increased in colorectal cancer patients compared to those in healthy control subjects." (PMID 22496788, 2012). "To compare the expression levels of HMGB1 in colorectal cancer tissues and adjacent normal mucosa, we firstly performed an immunohistochemical experiment using paraffin-embedded colorectal cancer tissues." (PMID 22496788, 2012). "We demonstrated that serum HMGB1 expression was approximately 1.2-fold higher in colorectal cancer patients than in healthy controls by the mean value, with high diversity between patients." (PMID 22496788, 2012). "Studies in other cancers, including colorectal cancer, nasopharyngeal carcinoma, and squamous-cell carcinoma of the head and neck, also showed that HMGB1 expression was inversely correlated with survival in late stage cancers but not in early stage caners." (PMID 22747650, 2012). "We identified that the concentration of serum HMGB1 was higher in patients with colorectal cancer than in normal healthy subjects." (PMID 22496788, 2012). "To calculate the ratio between HMGB1 secretion levels in colorectal cancer patients and those in healthy subjects, we quantified the band of western blot images by densitometry, with normalization using CBB (Coomassie Brilliant Blue) staining." (PMID 22496788, 2012). "The average serum HMGB1 levels were 1.5-fold higher (P = 0.03) in colorectal cancer patients; the mean serum concentration was 58.8±126.2 ng/mL in colorectal cancer patients and 39.7±16.2 ng/mL in control subjects." (PMID 22496788, 2012). "We found that the serum HMGB1 level was increased by 1.5-fold in patients with colorectal carcinoma compared to those in healthy controls." (PMID 22496788, 2012). "We, therefore suggest that the serum HMGB1 level is valuable in colorectal carcinoma detection, especially in combination with CEA." (PMID 22496788, 2012). "In this study, we evaluated serum HMGB1 concentrations in 219 patients with colorectal carcinoma and compared them to the concentrations in healthy control subjects." (PMID 22496788, 2012). "To evaluate the diagnostic significance of HMGB1, we compared HMGB1 levels with CEA levels and found that the combination of these two markers increases the diagnosis rate of early stage colorectal carcinomas." (PMID 22496788, 2012). "Our findings indicate that serum HMGB1 levels are increased in a subset of colorectal carcinomas, suggesting their potential utility as a supportive diagnostic marker for colorectal carcinomas." (PMID 22496788, 2012). "We herein demonstrated that HMGB1 is present in the blood of colorectal carcinoma patients, suggesting its utility in the early diagnosis of colorectal carcinomas." (PMID 22496788, 2012).